FRZB (frizzled related protein)
Diseases named in the same sentence as FRZB in open-access papers (continued):
Sharing a sentence is not in itself a finding about the gene and the disease.
Arthritis (3 papers, 2014 to 2018). Inflammation of a joint. "The two arthritis-susceptible candidate SNPs, rs7775 (p.Arg324Gly) in the FRZB gene and rs7033979 in the ASPN gene, showed associations with KBD (OR = 1.568, P = 4 × 10−3 and OR = 0.744, P = 8 × 10−3, respectively)." (PMID 28651521, 2017). "Our results are consistent with the increased cartilage loss observed in models of arthritis in FrzB−/− knockout mice." (PMID 24984954, 2014). "Moreover, gene expression of Mmp-3 was upregulated in the cartilage of FrzB−/− mice with mBSA-induced arthritis compared with wild-type mice." (PMID 24984954, 2014). "FrzB−/− knockout mice did not develop spontaneous OA, but the deletion of FrzB increased cartilage loss in three different models of arthritis." (PMID 24984954, 2014). "At the time of arthritis onset, SOST and DKK1 returned to control values, but frizzled related protein 1 (SFRP1), proinflammatory cytokines, and MMPs started to increase." (PMID 29472591, 2018).
hip osteoarthritis (3 papers, 2010 to 2022). "A single nucleotide polymorphism analysis demonstrated an association of hip osteoarthritis with an Arg324Gly substitution mutation in FrzB, a Wnt antagonist." (PMID 22151902, 2011). "Polymorphisms in the SFRP3 gene, which encodes Frizzled-related protein (FRZB), a secreted antagonist of the WNT signaling cascade, was found to be associated with hip osteoarthritis already in 2004, and mice lacking FRZB have increased susceptibility to OA." (PMID 36367882, 2022).
myeloma (3 papers, 2015 to 2023). "Previous literature data indicate that the deregulation of canonical Wnt signaling in myeloma cells causing overexpression of Dkk-1 or frizzled-related protein gene FRZB is associated with a high incidence of bone lesions in MM patients." (PMID 26579531, 2015). "For example, the expression of the WNT inhibitors, FRZB and DKK1 genes, is associated with osteolytic bone lesions in myeloma patients." (PMID 31748515, 2019). "In the case of multiple myeloma, myeloma cells secrete soluble mediators such as Dickkopf-related protein 1 (DKK1), activin A, and soluble frizzled-related protein 3 (sFRP3), which directly suppress osteoblastic bone formation." (PMID 36980681, 2023).
Obesity (3 papers, 2012 to 2023). Accumulation of substantial excess body fat. "Among them, a previous study showed that FRZB, which is involved in the signaling pathway, was downregulated in the placentae from women with obesity and obstructive sleep apnea." (PMID 37189386, 2023).
rheumatoid arthritis (3 papers, 2013 to 2023). A chronic, systemic autoimmune disorder characterized by inflammation in the synovial membranes and articular surfaces. "It is worth noting that our finding of FRZB differ from a prior study on circulating levels of FRZB in patients with early rheumatoid arthritis." (PMID 35368701, 2022).
atherosclerosis (2 papers, 2021 to 2025). A disease characterized by the build-up of fatty material and calcium deposition in the arterial wall resulting in partial or complete occlusion of the arterial lumen. "We also found certain HS disaccharides (D0H0) associated with APP and other proteins increased in CAA (OLFML3, FRZB, ApoE, FGA), as well as with ApoE genotype, but not with atherosclerosis." (PMID 40156913, 2025).
bladder cancer (2 papers, 2010 to 2023). "We identified and confirmed that increased promoter methylation of HOXB2 is significantly and independently associated with invasive bladder cancer and methylation of HOXB2, KRT13 and FRZB together significantly predict high-grade non-invasive disease." (PMID 20808801, 2010). "Methylation of HOXB2, FRZB and KRT13 is independently associated with high grade disease in non-invasive bladder cancer." (PMID 20808801, 2010). "In non-invasive bladder cancers, a significantly greater extent of HOXB2, FRZB, and KRT13 methylation was detected in grade 3 tumors as compared to grade 1 and 2 tumors." (PMID 37627900, 2023). "The methylation of HOXB2, FRZB, and KRT13 was greater in invasive bladder cancers as compared to non-invasive bladder cancers." (PMID 37627900, 2023). "Pyrosequencing was performed to determine the methylation status of HOXB2, FRZB, and KRT13 in bladder cancer cell lines HTB-9 and UM-UC3." (PMID 20808801, 2010). "HOXB2, FRZB, and KRT13 methylation status may be potential prognostic biomarkers to predict the likelihood of getting high grade non-invasive bladder cancer, that can subsequently be used to predict tumor recurrence or progression to muscle-invasion." (PMID 37627900, 2023).
cognitive disorder (2 papers, 2012 to 2025). A disease affects cognitive processes. "We suggest bU[−] patients are exposed to a higher risk of developing cognitive disorders based on the alteration of secreted frizzled-related protein 1 due to progressed type 2 diabetes, which can be identified using the proposed biomarker-based classification model." (PMID 40510539, 2025). "bU[−] displayed elevated markers of both Type 2 diabetes and cognitive disorders, specifically of secreted frizzled-related protein 1, a protein related to different neuronal pathologies." (PMID 40510539, 2025).
depression (2 papers, 2015 to 2024). "Interestingly, some of the linear dose-response DEGs have been implicated in transmission and plasticity (GRIN2A, GAD2), depression and antidepressant effect (DDIT4, GAD2) anxiety and stress responses (ADCYAP1R1), WNT signalling (FRZB), neurogenesis (ARHGEF39) and hippocampal volume (ANKRD37)." (PMID 39055655, 2024).
dilated cardiomyopathy (2 papers, 2023). Cardiomyopathy which is characterized by dilation and contractile dysfunction of the left and right ventricles. "FRZB has been identified as a hub gene in the HCM key module and hub biomarkers for dilated cardiomyopathy (DCM)." (PMID 38077583, 2023).
glioblastoma (2 papers, 2017 to 2024). The most malignant astrocytic tumor (WHO grade IV). "WNT4 and FRZB are two proteins involved in the Wnt signaling pathway, which regulates key cellular events during the development of the brain and is involved in the genesis of glioblastoma." (PMID 38612588, 2024).
ischemic cardiomyopathy (2 papers, 2023). Ischemic cardiomyopathy is a cardiomyopathy in which a weakness in the muscle of the heart due to inadequate oxygen delivery to the myocardium with coronary artery disease being the most common cause. "In addition, FRZB has been recognized as a potential immune-related key genes involved in ischemic cardiomyopathy through random forest analysis and nomogram." (PMID 38077583, 2023).
Myocardial fibrosis (2 papers, 2020 to 2021). "Similar to other potential novel biomarkers for myocardial fibrosis such as secreted frizzled-related protein, spermidine may have potential preventive or therapeutic value in myocardial fibrosis and HF." (PMID 34926616, 2021).
osteoporosis (2 papers, 2010 to 2021). A condition of reduced bone mass, with decreased cortical thickness and a decrease in the number and size of the trabeculae of cancellous bone (but normal chemical composition), resulting in increased fracture incidence. "Polymorphisms rs2242070 in FRZB gene was reported to be involved in the development of osteoporosis." (PMID 33820867, 2021).
psoriasis (2 papers, 2012 to 2025). An autoimmune condition characterized by red, well-delineated plaques with silvery scales that are usually on the extensor surfaces and scalp. "Likewise, the downregulation of the canonical wnt inhibitor DKK2, CTNNBIP1 (ICAT), Axin2, as well as FRZB (SFRP3) is common to SCC and psoriasis." (PMID 22384081, 2012).
age-related macular degeneration (1 paper, 2025). Age-related loss of vision in the central portion of the retina (macula), secondary to retinal degeneration. "In a study of the human ophthalmic disease Age-related Macular Degeneration (AMD), FRZB was identified as a mechanistic player in geographic atrophy, which is a form of AMD and is characterized by patchy degeneration of the retinal pigment epithelium and photoreceptors." (PMID 41226661, 2025).
amyotrophic lateral sclerosis (1 paper, 2022). Amyotrophic lateral sclerosis (ALS) is a neurodegenerative disease characterized by progressive muscular paralysis reflecting degeneration of motor neurons in the primary motor cortex, corticospinal tracts, brainstem and spinal cord. "FRZB is also a muscle biomarker of denervation atrophy in amyotrophic lateral sclerosis." (PMID 35850644, 2022).
aneurysm (1 paper, 2021). Bulging or ballooning in an area of an artery secondary to arterial wall weakening. "In pathway analysis with correlated genes with these two candidate genes (FRZB and C1orf24), we showed the pathways were related to VSMC and elastin fiber formation, which might imply these candidate genes are involved in aneurysm integrity." (PMID 33245093, 2021).
aortic aneurysm (1 paper, 2025). A ruptured aneurysm located in the wall of the proximal portion of the descending aorta proceeding from the arch of the aorta. "Interestingly, FRZB is also implicated in vascular processes such as protection against aortic aneurysms." (PMID 40156913, 2025).
behavioural disorder (1 paper, 2013). "Patients with heterozygous deletions that lie in this proximal region of 2q32 (including the FRZB gene) could be ascribed as having a general phenotype of LD/MR, some form of craniofacial dysmorphisms and a form of behavioural disorder." (PMID 23840981, 2013).
bladder tumors (1 paper, 2010). "For four of these loci (FRZB, STAT5A, KRT13, and HOXB2), bisulfite pyrosequencing assays were able to be designed, and were used to confirm the array findings in a subset of bladder tumors examined on the array." (PMID 20808801, 2010). "Pyrosequencing of the promoter regions of FRZB, KRT13, and HOXB2 was performed in an independent series of 263 bladder tumor patients not examined on the array as well as on 4 non-diseased tumor samples obtained from the NDRI." (PMID 20808801, 2010).
Down syndrome (1 paper, 2019). "In a cohort of patients with Down syndrome and AVSD, variants with the highest probability of being damaging in cases compared to Down syndrome patients without cardiac defects were in the VEGF-A pathway genes COL6A1, COL6A2, CRELD1, FBLN2, FRZB, and GATA5." (PMID 31888141, 2019).
ischaemic cardiomyopathy (1 paper, 2023). "This evidence strongly suggests that FRZB is significantly associated with cardiomyopathy development, but the relationship between FRZB and immune cells and ICM remains unclear." (PMID 36863704, 2023).
keloid (1 paper, 2024). An irregularly shaped, elevated mark on the skin caused by deposits of excessive amounts of collagen during wound healing. "For instance, keloid fibroblasts exhibited reduced levels of histone acetylation in the secreted frizzled-related protein 1 (SFRP1), resulting in upregulation of the Wnt (Wingless; Int1) signaling pathway and subsequently promoting keloid formation." (PMID 38338767, 2024).
knee osteoarthritis (1 paper, 2015). "Replication studies among Caucasian women showed two SNPs in sFRP3/FrzB gene, R200W (rs288326) and R324G (rs7775), may elevate knee osteoarthritis." (PMID 25945348, 2015).
liver cancer (1 paper, 2020). An epithelial or non-epithelial malignant neoplasm that arises from the liver. "However, the role of the WNT inhibitory factor secreted frizzled-related protein 1 (SFRP1) has not been addressed in pediatric liver cancer so far." (PMID 32189106, 2020).
lung fibrosis (1 paper, 2014). "We therefore studied the effect of SFRPs on lung fibrosis in in vitro and in vivo models, including the effect caused by absence of endogenous SFRP1 and FRZB in the bleomycin-induced lung fibrosis model." (PMID 25317206, 2014). "Based on these in vitro observations and the expression profile during bleomycin-induced lung fibrosis, we further studied the role of endogenous SFRP1 and FRZB using the respective knockout mice compared to wild-type (WT) littermates." (PMID 25317206, 2014). "Here, we studied the role of two extracellular Wnt antagonists, secreted frizzled-related protein-1 (SFRP1) and frizzled-related protein (FRZB) on lung fibrosis in vitro and in vivo." (PMID 25317206, 2014).
meningioma (1 paper, 2017). A generally slow growing tumor attached to the dura mater. "AQP1, FRZB, PDGFRL, and PECAM1 were consistently underexpressed in meningioma samples; MEDAG, MYC, PAMR1, PDPN and PERP were consistently overexpressed in nearly every meningioma sample by both measurements." (PMID 29073243, 2017). "Five genes that were down-regulated in the meningiomas compared to the control tissue included AQP1 (aquaporin 1), FRZB (Frizzled b), PECAM1 (platelet and endothelial cell adhesion molecule 1), PDGFRL (platelet-derived growth factor receptor-like), and FBLN2 (fibulin 2)." (PMID 29073243, 2017).
neuropathy (1 paper, 2020). A disorder affecting the nervous system that manifests with pain, tingling, numbness, and/or muscle weakness. "The neuropathy group had a similar mean fold-increase in FRZB, but similar to the mRNA analysis, there was high variance with some samples below the mean for the normal control group." (PMID 33028902, 2020).
Parkinson disease (1 paper, 2022). A progressive degenerative disorder of the central nervous system characterized by loss of dopamine producing neurons in the substantia nigra and the presence of Lewy bodies in the substantia nigra and locus coeruleus. "Other interesting associations reported in the GWAS catalogue include Parkinson’s disease (LZB3), educational attainment (FRZB and GLI3) and ADHD/Externalising behaviour (HERC1)." (PMID 36415660, 2022).
pituitary adenomas (1 paper, 2015). "A review of 13 whole genome approaches in pituitary tumors with the goal of identifying Wnt family inhibitors showed that expression of WF1, SFRP2, FRZB, SFRP4, DKK2, and SOSTDC1 genes is decreased in pituitary adenomas compared to normal pituitary tissue, while that of SFRP1 and SFRP4 is increased." (PMID 25834571, 2015).
Renal clear cell carcinoma (1 paper, 2021). "Renal clear cell carcinoma-derived miR-27a-loaded exosomes inhibit secreted frizzled-related protein 1 (SFRP1) expression and accelerate tumor angiogenesis." (PMID 34211501, 2021).
renal fibrosis (1 paper, 2020). A final common manifestation of a wide variety of chronic kidney diseases characterized by glomerulosclerosis and tubulointerstitial fibrosis. "This work aimed to investigate whether miR-27a can promote the occurrence of renal fibrosis in DN by suppressing the expression of secreted frizzled-related protein 1 (Sfrp1) to activate Wnt/β-catenin signalling." (PMID 32484208, 2020).
retinoblastoma (1 paper, 2025). A malignant tumor that originates in the nuclear layer of the retina. "Among the most upregulated genes were KRT5, KRT19, LCN2, SLP1 and S100A9, while GNAT1, PDE6G, WIF1, FRZB, and RHO were among the top downregulated genes in retinoblastoma." (PMID 40395327, 2025).
tendinopathy (1 paper, 2011). "Additionally, tendinopathy tissue showed differential expression of other WNT pathway genes, including increased expression of CTNNB (1.5-fold), WNT5a (2.7-fold), and FZD1 (1.7-fold) and decreased expression of LRP5 (0.59-fold) and FRZB (0.35-fold)." (PMID 21539748, 2011).
tumor (41 papers, 2004 to 2025). "FRZB expression wassignificantly down-regulated in different subgroups of HNSCC patients, includingTP53 mutation status, HPV status, metastasis,gender, and tumor grade and stage,indicating that FRZB may be a potential biomarker for patients with HNSCC." (PMID 38775547, 2024). "In this study, we found that FRZB was dysregulated inHNSCC tumor tissues and had a relationship with clinical parameters." (PMID 38775547, 2024). "Lasso regression analysis was subsequently used to screen forprognostic variables, and we determined the infiltration of immune cells inHNSCC patients to clarify the influence of FRZB on tumor immunemicroenvironment." (PMID 38775547, 2024). "The secreted frizzled-related protein 1 and 2 genes (SFRP1 and SFRP2) encode antagonists of the Wnt signaling pathway, acting as tumor suppressors." (PMID 33030559, 2021). "In the m ore aggressive MM and UM there was a concomitant strong upregulation of the Wnt signaling antagonists dickkopf 3 and secreted frizzled-related protein (frzB), while in the XE tumor only a slight upregulation of frzB was noted." (PMID 22693581, 2012). "The Fzd8 soluble extracellular domain suppresses Wnt-driven tumor growth in vivo and two sFRPs, FrzA and FrzB inhibited Wnt-1–mediated increase in cytoplasmic β-catenin levels, TCF transcriptional activity in vitro, and tumor growth and metastasis." (PMID 22606268, 2012). "Furthermore, FRZB considerably suppresses tumor growth and invasion through the inhibition of Wnt/β-catenin pathway." (PMID 38833013, 2024). "Moreover, Wnt signaling-related genes such as CD133 and β-catenin expression were up-regulated and Frizzled related protein (FRP) was down-regulated during the tumor development of ESCs." (PMID 22995718, 2012). "Proteins associated with tumor progression or a bad prognosis such as WNT5A, MMP13, MMP3, telomerase, and NOTCH3 were upregulated while proteins associated with immune cell infiltration or pathway inhibitors/tumor suppressors such as FRZB, CD177, PPARG, and HRASLS2 were downregulated." (PMID 38504345, 2024). "The protein products of FRZB and RBM24 have tumor suppressive roles in colorectal and other cancers." (PMID 40753397, 2025). "Within the realm of known WNT antagonists, the secreted frizzled-related protein 1 (SFRP1) frequently experiences downregulation across various cancer types, implying its tumor-suppressive functions." (PMID 38390281, 2024). "SFRP5 is a member of the secreted frizzled-related protein (SFRP) family and acts as a tumor suppressor and a secreted antagonist of the Wnt/β-catenin pathway." (PMID 37894456, 2023). "The sFRP family contains five glycoproteins, SFRP1, SFRP2, SFRP3 (FRZB), SFRP4, and SFRP5, which are generally regarded as tumor suppressors owing to their ability to negatively regulate the Wnt pathway." (PMID 35204808, 2022). "Using the same data cohort, another study found that Secreted frizzled-related protein 3 (SFRP3), a putative tumor suppressor in LUAD, is epigenetically silenced and is associated with poor prognosis." (PMID 29746588, 2018). "Here we demonstrated retained protein expression of well-known Wnt inhibitor, secreted frizzled-related protein 1 (SFRP1) in stromal myofibroblasts and decreasing epithelial expression from NAT tissues towards the tumor." (PMID 25405986, 2014). "In order to furtherverify whether FRZB expression level in HNSCC was lower, we used TCGA datasets.From the obtained results, the expression of FRZB was decreased in tumor tissuescompared with adjacent normal tissues." (PMID 38775547, 2024).